LILRB1 (leukocyte immunoglobulin like receptor B1)
Diseases named in the same sentence as LILRB1 in open-access papers (continued):
Sharing a sentence is not in itself a finding about the gene and the disease.
hematological malignancies (6 papers, 2014 to 2025). "However, further investigations are needed to examine MHC-I expression patterns in hematological malignancies and LILRB1/2 expression patterns in associated TAMs." (PMID 35978372, 2022). "In this study, we identified LILRB1 as a novel target for CAR-T cell immunotherapy of hematologic malignancies." (PMID 40186066, 2025). "Based on our results, we demonstrate for the first time that LILRB1 is a viable target for immunotherapy and propose LILRB1 CAR-T cells as a prototype for a novel strategy applicable across various hematologic malignancies." (PMID 40186066, 2025). "LILRB1 blocking antibodies have been used to explore the biology of LILRB1 mediated immune suppression in hematologic malignancies." (PMID 39696628, 2024). "Clinical research studies are also needed to examine the clinical efficacy of blocking the MHC-I/LILRB1/2 axis in hematological malignancies." (PMID 35978372, 2022). "Thus, LILRB1 represents an attractive target antigen for cell-based immunotherapy to treat different hematological malignancies, including challenging cases previously treated with other lines of treatment." (PMID 40186066, 2025). "Non-classic class I HLAs, ligands of LILRB1 and LILRB2, are integral components of the disease microenvironment in multiple hematologic malignancies." (PMID 39696628, 2024).
adenocarcinoma (2 papers, 2022 to 2023). A common cancer characterized by the presence of malignant glandular cells. "In adenocarcinoma, there is a positive association between LILRB1 expression and advanced pathological stage of malignancy." (PMID 35076022, 2022). "LILRB1 may also be considered as a diagnostic and prognostic target in gastric cancers, in addition to certain subtypes of adenocarcinoma." (PMID 35076022, 2022).
immune system disorder (1 paper, 2016). A disorder resulting from an abnormality in the immune system. "Of interest, deletion polymorphism encompassing the large part of LILRA3, a soluble receptor which possibly antagonizes binding of sHLA-G and LILRB1/LILRB2, has been associated with a variety of immune system disorders." (PMID 27331404, 2016).
infectious disease (1 paper, 2024). A disorder directly resulting from the presence and activity of a microbial, viral, or parasitic agent in humans. "Finally, LILRB1, LILRB2, and Tim3 expressions were evaluated as key inhibitory receptors implicated in the balance between parasite immune evasion and immune responses to infectious diseases." (PMID 38835780, 2024).
LILRB1 also shares sentences with these, for which no sentence is quoted: colorectal cancer (5 papers); lung carcinoma (4); triple-negative breast carcinoma (4); non-small cell lung carcinoma (3); renal cell carcinoma (3); cervical cancer (2); Graves disease (2); head and neck squamous cell carcinoma (2); influenza (2); liver cirrhosis (2); lymph node metastasis (2); schizophrenia (2); allergic rhinitis (1); Allergy (1); Angina (1); aplastic anaemia (1); asthma (1); autism (1); B-cell acute lymphoblastic leukemia (1); bladder cancer (1); bladder tumor (1); Burkitt lymphoma (1); cardiomyopathy (1); chronic hepatitis B (1); Cirrhosis (1); colon mucinous adenocarcinoma (1); diabetics (1); diphtheria (1); endometrial cancer (1); endothelial dysfunction (1).
A further 35 diseases each share a sentence with LILRB1 in 1 paper.